LCN2 (lipocalin 2)
Diseases named in the same sentence as LCN2 in open-access papers (continued):
Sharing a sentence is not in itself a finding about the gene and the disease.
steatosis (16 papers, 2016 to 2025). Increased lipid within the cytoplasm of cells. "LCN2 is a downstream TNF inflammatory molecule associated with hepatic steatosis and insulin insensitivity." (PMID 31892368, 2019). "Our analysis of liver tissues by Western blot suggested an increased susceptibility to steatosis conferred by LCN2 deficiency." (PMID 29234288, 2017). "In our study, steatosis occurred in response to fructose treatment, especially in female and LCN2 deficient mice." (PMID 29234288, 2017). "It is tempting to speculate that WT mice exposed to fructose for a longer period would be more affected by this sugar, and that a deficiency in LCN2 confers greater susceptibility to steatosis induced by fructose." (PMID 29234288, 2017). "It has been previously reported that Lcn2 knockout mice are protected from alcohol-induced steatosis and liver injury." (PMID 39337294, 2024). "As revealed by logistic regression, improvement in steatosis grade was also correlated with LCN2 decrease." (PMID 35034646, 2022). "The decrease in LCN2 levels was significantly related to the reduced hepatic fat content and improvement in steatosis grade after adjusting for gender, age, and BMI decrease." (PMID 35034646, 2022). "Hepatic damage and steatosis were also reported to be prominent in LCN2−/− mice under high-fructose diet by Lambertz and colleagues." (PMID 35034646, 2022). "Further in vivo, in vitro and clinical studies are necessary to unveil the multiple roles of LCN2 in steatosis and iron dysregulation during inflammation." (PMID 36012166, 2022). "The highest grade of steatosis was obtained in female LCN2 KO mice that had received fructose-enriched chow for 8 weeks." (PMID 29234288, 2017). "Since LCN2 regulates hepatic lipid uptake, this finding also explains our observation that fructose-exposed LCN2 KO females suffer from more severe steatosis than do WT females." (PMID 29234288, 2017). "To determine the roles of LCN2 and PLIN5 in the formation and progression of steatosis and NAFLD, we examined the liver biology of WT and LCN2-deficient male and female mice subjected to regimens designed to increase their fructose intake over 4 or 8 weeks." (PMID 29234288, 2017). "In this case, female mice developed more steatosis than males, although LCN2 KO males suffered more damage than WT males." (PMID 29234288, 2017). "Accumulating evidence suggests that the altered expression of LCN2 plays critical roles in several pathological organ conditions, including liver injury and steatosis, renal damage, brain injury, cardiomyopathies, musculoskeletal disorders, lung infection, and cancer in several organs." (PMID 36012166, 2022). "The altered expression of LCN2 could trigger disease in several pathologic organs, including liver injury, steatosis, kidney injury, brain injury, cardiomyopathy, musculoskeletal disease and cancer of several organs." (PMID 33686952, 2021). "Because we previously observed that Lcn2-deficient mice are more prone to hepatic damage, we expected more severe steatosis in mice lacking LCN2 after prolonged feeding of fructose." (PMID 29234288, 2017). "Moreover, LCN2 expression is being considered as a potential strong biomarker for pathological conditions, including rheumatic diseases, cancer in human organs, hepatic steatosis, hepatic damage, and inflammation." (PMID 27729871, 2016). "In steatotic conditions, serum LCN2 levels are significantly increased in patients with MASLD, correlating with the degree of steatosis." (PMID 39832399, 2025). "The area under the ROC curve of serum LCN2 was 0.987 with a specificity of 100% and a sensitivity of 93.5% for NASH diagnosis, and 0.977 with almost the same specificity and sensitivity for steatosis." (PMID 33799862, 2021). "This study showed that LCN2 is overexpressed in mice with NASH, together with chemokines CXCL1 and CXCL9, while their overexpression was missed in mice with steatosis." (PMID 33799862, 2021).
steatosis (continued). "In addition, compared with WT mice with a high-fat diet (HFD) to induce simple steatosis, HFD-fed ob/ob mice (models of NASH) had higher hepatic expression of LCN2 and larger Sirius Red-stained fibrotic areas." (PMID 37784089, 2023). "We found that fructose-induced steatosis and liver damage was more prominent in female than in male mice, but that the most severe hepatic damage occurred in female mice lacking LCN2." (PMID 29234288, 2017). "LCN2 is a reliable indicator of hepatic damage and positively correlated with inflammation; therefore, the elevation of Lcn2 in the livers of L1-Tg mice fed a HFD supports a previous study that shows that the activation of innate immune systems is related to hepatic NPC1L1-mediated steatosis." (PMID 31883528, 2019).
liver cirrhosis (15 papers, 2015 to 2024). "CCL20 and LCN2 were determined in all samples (HCC, 167; liver cirrhosis, 106; and healthy control, 106) and finally chosen for the construction of the combination model by binary logistic regression." (PMID 35308139, 2022). "We finally evaluated the performance of the CCL20/LCN2-based model (model_2) in discriminating HCC from the comprehensive control that includes all nontumor subjects and the control of patients with liver cirrhosis, which constitutes the highest risk group for the development of HCC." (PMID 35308139, 2022). "Moreover, they found that LCN2 levels are able to discriminate between HCC and liver cirrhosis subjects, and they also proved that LCN2 levels are not suitable to distinguish between early and late HCC." (PMID 33799862, 2021).
nephritis (15 papers, 2013 to 2025). Inflammation of renal tissue. "To quantify the diagnostic utility of urinary lipocalin-2 as marker of nephritis in patients, we constructed an ROC curve, using urinary lipocalin-2/creatinine in patients with LN proven by biopsy (the current gold standard) and patients without nephritis." (PMID 24171081, 2013). "Upregulated LCN2 in nephritic mice promotes IFN-γ and enhances inflammation, and the anti-LCN2 antibody can effectively alleviate nephritis." (PMID 38072118, 2023). "Using a cutoff value of 0.39 ng /mg, urinary lipocalin-2/creatinine had a sensitivity of 89.7% and a specificity of 39.1% for identifying patients with biopsy-proven nephritis." (PMID 24171081, 2013). "Urinary lipocalin-2/creatinine sensitivity and specificity for identifying biopsy-proven nephritis were calculated, and a receiver operating characteristic (ROC) curve was constructed." (PMID 24171081, 2013). "Similarly, a crucial role of LCN2 was proven in a mouse model of nephrotoxic nephritis in which the injection of LCN2 promoted inflammation, apoptosis, and exacerbated nephritis." (PMID 27729871, 2016).
oral cancer (15 papers, 2015 to 2025). "Similarly, loss of LCN2 in oral cancer cell lines leads to a decrease in EGFR recycling and a decrease in invasion." (PMID 40356520, 2025). "Interestingly, some of these proteins (as S100 proteins and LCN2) are described as diagnostic and prognostic markers for several types of tumors, even though their role in oral cancer is controversial." (PMID 34681822, 2021). "In this regard, the value of chemopreventive interventions targeting LCN2 may increase over time, as the fraction of oral cancers that are linked to HPV infection continues to increase." (PMID 25635769, 2015). "In this case, the mechanistic target of the Rapamycin (mTOR) pathway is activated when LCN2 is silenced, leading to oral cancer progression." (PMID 33799862, 2021). "In these studies, patients with high levels of LCN2 had better survival outcomes, making LCN2 a good prognostic factor in oral cancer." (PMID 33604288, 2020). "LCN2 expression was reported to be downregulated in oral cancer, and was further reduced in oral cancer with metastasis." (PMID 33604288, 2020). "Surprisingly, vitamin D exposure made oral cancer cells again sensitive to cisplatin by inhibiting LCN2 expression and Nf-kB phosphorylation." (PMID 32560347, 2020). "Further research needs to expand the sample size to more clearly define the relationship between LCN2 expression and survival in oral cancer patients with recurrence." (PMID 31819048, 2019). "This idea is further supported by reports that (a) lipocalins such as LCN2 and several chemokines are significantly overexpressed in human oral cancers and (b) these and related targets appear to be “druggable”." (PMID 25635769, 2015). "Furthermore, considering that LCN2 overexpression is associated with lymph node metastasis, poor prognosis and post-chemotherapy recurrence, oral cancer cell lines overexpressing LCN2 proteins showed less sensitivity to cisplatin." (PMID 32560347, 2020). "The mechanism through which LCN2 exerts its anti-tumor effects in oral cancer may be related to a reduction in autophagy mediated through mTOR signaling pathway activation." (PMID 33604288, 2020). "Similarly, oral cancer cells (CAL-27 & SCC-9 cell lines) treated with vitamin D showed a partial reversion of cisplatin resistance through lipocalin-2 (LCN2) protein downregulation." (PMID 32560347, 2020). "Taken together, the observed upregulation of LCN2 in oral cancers and its apparent upregulation by HPV infection suggest that this gene may provide a mechanistically relevant target for the prevention of oral neoplasia induced by HPV." (PMID 25635769, 2015). "Furthermore, knock-down of LCN2 led to increased viability of oral cancer cells." (PMID 35371305, 2022). "Furthermore, when considered with the proproliferative, antiapoptotic, and proinflammatory effects of LCN2, these data suggest that LCN2 and/or other lipocalins may provide useful targets for the design of novel agents for oral cancer chemoprevention." (PMID 25635769, 2015).
brain tumors (14 papers, 2009 to 2025). "Intracranial injection of PC9-BM cells with LCN2 knockdown resulted in markedly reduced the brain tumor burden compared to controls (P < 0.01)." (PMID 41436606, 2025). "Exosomes from primary brain tumors have demonstrated increased expression of Lipocalin-2 (LCN2) in bEnd.3 brain microvascular endothelial cells." (PMID 38287384, 2024).
Cachexia (14 papers, 2019 to 2026). Severe weight loss, wasting of muscle, loss of appetite, and general debility related to a chronic disease. "Overall collected data suggest that adipocyte-related Lcn2 participates as stress responsive protein during inflammatory conditions associated with cachexia-like states." (PMID 37517520, 2023). "LCN2 is a prognostic marker of cancer-associated cachexia (CAC) and its downregulation improve CAC symptoms." (PMID 37517520, 2023). "To get a better idea of which of the identified cachexia genes found with the scRNAseq are caused by LCN2 induction, we generated heatmaps of those differentially expressed genes from the LCN2 RNA-seq data for endothelial cells, microglia and oligodendrocytes." (PMID 35031523, 2022). "Using five separate murine models of pancreatic ductal adenocarcinoma-associated cachexia, we measured daily food intake, skeletal and cardiac muscle mass, and circulating and central LCN2 levels." (PMID 33824339, 2021). "To investigate whether circulating LCN-2 levels are associated with specific cachexia features in PDAC patients, we performed correlation analyses." (PMID 37006254, 2023). "Furthermore, antibody depletion of tissue-infiltrating neutrophils (TI-Neu), as well as myeloid-specific-knockout of Lcn2, were undertaken to reveal if LCN2 secreted by TI-Neu caused cachexia." (PMID 36973755, 2023). "We show that the genetic deletion of Lcn2 mitigates cachexia–anorexia and lean and fat mass loss, while restoration of LCN2 in the bone marrow compartment alone reestablishes the anorexia and muscle catabolism features of cachexia." (PMID 33824339, 2021). "However, LCN2 in the hypothalamus interacts with the melanocortin-4 receptor, which has been shown to mediate anorexia and promote the loss of lean (skeletal muscle) and fat (adipose tissue) mass in cancer cachexia." (PMID 36973755, 2023). "Lcn2 was among the most highly upregulated transcripts in the hypothalamus and was recently implicated in the suppression of food intake, one of the key symptoms of cachexia, but its exact function is still unknown." (PMID 35031523, 2022). "Recently, several new cachexia-related factors, such as the growth factor GDF15 and the chemokine LCN2, which participate in cachexia through mechanisms that amplify inflammatory signals beyond traditional pathways, have been reported." (PMID 41526343, 2026). "We found a marked increase in LCN2 expression along with a shut-down of PD-1/CD112R expression only at the most advanced stage of cachexia, during which we observed anorexia and sustained increases in cytokine production that began in the pre-cachexia stage." (PMID 38685046, 2024). "Histology showed that treatment with anti-LCN2 antibody also alleviated the pathological morphology of iWAT and Gast of cachexia model mice." (PMID 36973755, 2023). "Second, the neutrophils of cancer patients with cachexia had significantly higher LCN2 levels than other immune cells (monocytes, T cells, NK cells, and B cells)." (PMID 36973755, 2023). "To find more proof that LCN2 primarily affects endothelial cells, oligodendrocytes, and immune cells in the MBH under cachectic conditions, we used TB Lcn2 KO mice to determine if removal of Lcn2 affects our cachexia marker genes in these cell populations." (PMID 35031523, 2022). "In accordance with this, TB Lcn2 KO mice showed a reduced induction of cachexia markers in endothelium, microglia, and oligodendrocytes during cachexia compared with TB WT mice." (PMID 35031523, 2022). "First, we found that Lcn2 KO mice had more moderate cachexia and correspondingly decreased induction of a subset of the DE genes found in our scRNAseq model, such as Plin4, Tmem252, and Ly6a." (PMID 35031523, 2022). "We show that Lcn2, the highest induced gene, has an important role in mediating various features of cachexia, and our RNA-seq precisely depicts its role in endothelial inflammation and activation of various components of the immune system." (PMID 35031523, 2022).
Cachexia (continued). "Although deletion of LCN2 improves cachexia–anorexia, direct pharmacologic inhibition of LCN2 in the CNS during cachexia is outstanding, particularly in the context of the putative LCN2-MC4R axis during disease." (PMID 33824339, 2021). "To determine if LCN2 is an inflammation-induced mediator of cachexia, we examined circulating LCN2 levels in both Il-6 and Myd88 knockout mice, as these two inflammatory signaling pathways are critical in the development of several features of cachexia." (PMID 33824339, 2021). "After our initial characterization of LCN2 production across five separate models of cachexia, we focused on the well-characterized KPC model for ensuing genetic and pharmacologic studies." (PMID 33824339, 2021). "In this case, it is plausible that bone-derived LCN2 15, contributes significantly to circulating levels during cachexia." (PMID 33824339, 2021). "As the bone marrow is a primary lymphoid organ responsible for the generation of immune cells, we went on to identify neutrophils as a significant source of LCN2 during cachexia." (PMID 33824339, 2021). "During both normal physiology and cachexia, we observed LCN2 principally in the bone marrow compartment, with much smaller quantities observed in the spleen, lung, and liver." (PMID 33824339, 2021). "Is peripherally produced LCN2 able to directly modulate metabolism, as described in previous reports, during cachexia progression?" (PMID 34439145, 2021). "While we believe the majority of LCN2 during cachexia is neutrophil-derived, it is conceivable that our BMT experiments also repopulated bone-resident cells." (PMID 33824339, 2021). "Furthermore, experiments using LCN2 knockout mice have shown that suppression of LCN2 can alleviate the cachexia phenotype of decreased food intake." (PMID 38685046, 2024). "Moreover, histology showed that neutrophil depletion alleviated the pathological morphology of iWAT, eWAT, and Gast observed in cachexia model mice and also reduced the LCN2 levels in the eWAT, iWAT, Gast, and serum significantly." (PMID 36973755, 2023). "In addition, after sacrificing the mice, a qPCR analysis showed significantly increased Lcn2 expression in the tissues (eWAT, iWAT, and Gast) of cachexia model mice; eWAT, iWAT, and Gast undergo atrophy in cachexia." (PMID 36973755, 2023). "Furthermore, the number of neutrophils in the blood of cancer patients suffering from cachexia correlated positively with their LCN2 level, but negatively with their BMI." (PMID 36973755, 2023). "Interestingly, cerebral treatment with LCN2 not only induced many of the observed molecular changes in cachexia but also affected gene expression in food-intake decreasing POMC neurons." (PMID 35031523, 2022). "Taken together, the robust increase in neutrophil count, along with the modest elevation of intracellular LCN2 levels and increase in Lcn2 expression in neutrophils, all support the notion that neutrophils are a significant source of circulating LCN2 levels during cachexia." (PMID 33824339, 2021). "Furthermore, restoration of Lcn2 expression in the bone marrow yielded a near 50% restoration of LCN2 levels in the CSF during both normal physiology and cachexia." (PMID 33824339, 2021). "Furthermore, restoration of Lcn2 in the bone marrow compartment is sufficient to rescue the cachexia–anorexia phenotype." (PMID 33824339, 2021). "Specifically, is CNS inflammation requisite in LCN2 MC4R-dependent effects during cachexia?" (PMID 34439145, 2021). "Taken together, we present an immunometabolic mechanism of appetite regulation during cachexia in which LCN2 is derived from the bone marrow compartment, crosses the BBB, and binds to the MC4R in mediobasal hypothalamic neurons to mediate long-term anorexia and subsequent loss of lean and fat mass." (PMID 33824339, 2021).